Y_RNA (Y RNA )
Gene: Miscellaneous RNA gene on chromosome X (19,376,774 to 19,376,875, forward strand). Ensembl gene ENSG00000202144.
Homologues: Orthologues: chimpanzee Y_RNA (100% identical), macaque Y_RNA (95% identical), guinea pig Y_RNA (92% identical). Paralogues in human: Y_RNA (89% identical), Y_RNA (88% identical), RNY3 (87% identical), Y_RNA (87% identical), Y_RNA (86% identical), Y_RNA (85% identical), RNY3P1 (84% identical), Y_RNA (84% identical), Y_RNA (83% identical), RNY3P16 (82% identical), Y_RNA (82% identical), RNY3P14 (81% identical), and 96 more.